CHD5 (chromodomain helicase DNA binding protein 5)
Diseases named in the same sentence as CHD5 in open-access papers (continued):
Sharing a sentence is not in itself a finding about the gene and the disease.
cancer (continued). "Increasing evidence shows that CHD5 plays a critical role in human cancer initiation and progression." (PMID 33062682, 2020). "KDM4A is abnormally expressed in cancer, affecting the expression of multiple targets, such as the CHD5 gene." (PMID 29682202, 2018). "Some authors have reported that DNA methylation at CHD5 gene promoter can alter the expression of this gene in several cancers and neoplastic cell lines." (PMID 29682202, 2018). "We firstly examined the expression levels of multiple cancer genes in RCC cells with ectopic CHD5 expression, including oncogenes, epigenetic master genes, epithelial-mesenchymal transition (EMT) and stem cell-related genes." (PMID 26943038, 2016). "There are reports that CHD5 acts as a TSG in other cancers, such as breast, colon, lung prostate, ovary and others." (PMID 26245651, 2015). "The findings of our study suggest that CHD5 promoter methylation is a mechanism for controlling CHD5 expression in human cancer." (PMID 24454811, 2014). "In summary, our study shows that human CHD5 functions as a bona fide transcriptional repressor and identifies a CHD5-dependent transcription pathway in cancer cells." (PMID 25247294, 2014). "In adults, expression of CHD5 is frequently lost in a variety of cancers either due to deletions of chromosome 1p36.3 or due to CHD5 promoter CpG-hypermethylation." (PMID 25247294, 2014). "While the links between CHD5 and cancer progression are rapidly emerging, the role of CHD5 in cells remains poorly understood." (PMID 25247294, 2014). "Elucidation of the molecular mechanism by which CHD5 modulates these processes will expectedly open new avenues for targeted cancer therapy in NB." (PMID 24709709, 2013). "Compared to HMEC, 20 of 32 cancer cell lines (62.5%) showed reduced expression of CHD5 by at least 50%, and 17 (53.1%) had an reduction by at least 75%." (PMID 22569290, 2012). "CHD5 was previously thought to be specifically expressed in the nervous system, but its role in cancer in other tissues is starting to emerge." (PMID 19840376, 2009). "CHD5 protein expression was evaluated in moderate to well differentiated and poorly differentiated carcinomas compared to matched normal tissue using TMA." (PMID 19750230, 2009). "Additionally, in various other malignancies, CHD5 can also exert anti-cancer effects, either through direct DNA binding or by functioning as a transcription factor." (PMID 41487470, 2026). "In conclusion, CHD5 was found to be differentially expressed in the pan-cancer analysis and might play an important role in antitumor immunity." (PMID 35955624, 2022). "Our results also showed that the expression of CHD5 was upregulated in some cancer types." (PMID 35955624, 2022). "To further investigate the correlation between CHD5 expression and prognosis, we performed a survival analysis for 33 types of cancers using the following metrics: overall survival (OS), disease-free survival (DSS), disease-free interval (DFI) and progression-free interval (PFI)." (PMID 35955624, 2022). "In summary, our pan-cancer analysis revealed that CHD5 was abnormally expressed in cancer samples across different types of cancers, and the abnormal expression of CHD5 correlated with the clinicopathological features and patient prognosis, especially in tumors related to the nervous system." (PMID 35955624, 2022). "CHD5 is also a known tumor suppressor gene frequently deleted or silenced in diverse human cancers." (PMID 33944996, 2021). "Epigenetic silencing of CHD5 through methylation has been observed in multiple cancer types." (PMID 31769422, 2019). "It is possible that CHD5 plays an essential role in cancer development." (PMID 29907144, 2018). "Several results indicate that the chromatin remodeling function of CHD5 might be important for preventing cancer." (PMID 24454811, 2014).
cancer (continued). "In addition to regulating processes that are fundamental for cancer prevention, CHD5 expression is also a favorable predictor of survival following anticancer therapy." (PMID 24454811, 2014). "Promoter hypermethylation of CHD5 in cancer has been observed in other cancers." (PMID 19840376, 2009). "Furthermore, the expression of CHD5 was correlated with TMB in 12 types of cancers." (PMID 35955624, 2022). "Therefore, downregulation of CHD5 may be a critical initiating molecular event in tumorigenesis and represent a prognostic biomarker of outcome in patients with cancer." (PMID 33062682, 2020). "In one study analyzing CHD gene promoter methylation in various cancer cell lines, out of all CHD genes, CHD5 promoter was methylated the most often, although the OC cell line (MDAH2774) showed no increase in methylation." (PMID 36430148, 2022). "In this study, we analyzed the expression of CHD5 and its relationship with the prognosis, TMB and MSI in 33 cancer types." (PMID 35955624, 2022). "ACTL6A, CHD2, and ACTB had the highest pan‐cancer G‐score for amplification, whereas CHD5, SHPRH, INO80, and ACTR8 had the highest pan‐cancer G‐score for deletions." (PMID 35789070, 2022). "Given the expression of CHD5 was restricted to the transcriptional level, and its function at the protein level might have a major impact on cancer progression, it is critical to further explore the effect of the protein expression of CHD5 across different types of cancers." (PMID 35955624, 2022). "IHC analysis showed that low CHD5 expression correlated with worse patient outcomes in PDAC, and similar results were observed in other cancers." (PMID 31769422, 2019). "In the remaining three cancer cell lines (BRF-71T, HCC38 and BT-549), CHD5 promoter methylation was detectable but to a much lower extent." (PMID 22569290, 2012). "In conclusion, our study confirms the hypermethylation of cancer candidate genes as biomarkers and a higher methylation profile of GPNMB, ICAM5, and CHD5 genes in AA was observed." (PMID 19750230, 2009). "Besides CHD5, CHD CRCs are also found to be dysregulated in ovarian and other cancers and have a role in chemoresistance." (PMID 36430148, 2022). "We also reported that the promoter of CHD5 is frequently methylated in NBs with low or absent CHD5 expression, and suppression of CHD5 expression by promoter methylation has been found in other cancers as well." (PMID 26245651, 2015). "CHD5 resides on the chromosomal locus 1p36 and has been reported to be silenced by genetic lesions, promoter DNA hypermethylation, histone demethylase JMJD2A, and micro-RNA 211 in many cancers." (PMID 26517514, 2015). "Recent studies have indicated that CHD5 expression is epigenetically silenced by hypermethylation of the CHD5 promoter in cancer cells in which the CHD5 gene is not deleted." (PMID 24454811, 2014). "As CHD5 shares the same functional domain with CHD3 and CHD4, it may also modulate chromatin remodeling and thus affect normal development and cancer." (PMID 22569290, 2012). "Our findings showed that CHD5 expression was positively correlated with MSI in 5 types of cancers, including LUSC, LUAD, ACC, LGG, and CESC, but was not negatively correlated with any of the cancer types." (PMID 35955624, 2022).
neurodevelopmental disorder (2 papers, 2021 to 2025). A behavioral and cognitive disorder with onset during the developmental period that involves impaired or aberrant development of intellectual, motor, or social functions. "Finally, CHD5 mutations have recently been identified as causing a neurodevelopmental disorder that is clinically very similar to those associated with CHD3 and CHD4 mutations." (PMID 40004235, 2025).
psychiatric disorder (2 papers, 2021 to 2024). A disorder characterized by behavioral and/or psychological abnormalities, often accompanied by physical symptoms. "The gene encoding CHD5 was also found to be a shared risk locus in ASD and two psychiatric disorders, fitting the observation that the effects of CHD5 deletion in mouse were consistent with the presentation of ASDs." (PMID 34828433, 2021).
Heart Disease (1 paper, 2014). "Two allelic mutations (9R9 and 13P2) affect CG32022, a gene that encodes a homolog of human Congenital Heart Disease 5 (Chd5)/Tryptophan-rich basic protein (Wrb), which is required for protein insertion into the endoplasmic reticulum membrane." (PMID 24531791, 2014).
infection (1 paper, 2021). The state of being infected such as from the introduction of a foreign agent such as serum, vaccine, antigenic substance or organism. "ZGPAT and CHD5 were found only in leukocytes with H37Rv strain infection." (PMID 34141493, 2021).
neurodegenerative disease (1 paper, 2018). A disorder of the central nervous system characterized by gradual and progressive loss of neural tissue and neurologic function. "CHD5 is an essential factor for neuronal differentiation and neurodegenerative diseases." (PMID 29861839, 2018).
CHD5 also shares sentences with these, for which no sentence is quoted: non-small cell lung carcinoma (3 papers); craniosynostosis (2); autism (1); behavioral disorder (1); cervical squamous cell carcinoma (1); CNS tumors (1); diabetes (1); hematopoietic neoplasms (1); iron deficiency (1); iron deficiency anaemia (1); kidney cancer (1); laryngeal squamous cell carcinoma (1); malignant mesothelioma (1); neuroblastic tumor (1); non-Hodgkin lymphoma (1); oral carcinoma (1); prostate tumors (1); renal carcinoma (1); renal cell carcinoma (1); small cell lung carcinoma (1); Speech apraxia (1); speech delay (1); stomach cancer (1); stress-related disorder (1); T-cell acute lymphoblastic leukemia (1).